PROS1 (protein S)
Diseases named in the same sentence as PROS1 in open-access papers (continued):
Sharing a sentence is not in itself a finding about the gene and the disease.
Thrombocytopenia (6 papers, 2014 to 2025). A reduction in the number of circulating thrombocytes. "Clinically, protein S deficiency was associated with defective liver function and complications of liver dysfunction including high variceal degree, variceal bleeding, thrombocytopenia, prolongation of prothrombin time, hyperbilirubinemia, and high MELD score." (PMID 32326024, 2020). "In this study, prolongation of prothrombin time, thrombocytopenia, and relative deficiency of protein C and protein S levels were widely observed while these patients were waiting for liver transplantation." (PMID 32326024, 2020). "The patient was found to be allergic to nickel, protein S deficient and carrier of heparin-induced thrombocytopenia antibody." (PMID 26207097, 2015). "Chronic low levels of protein C and protein S and thrombocytopenia were found in 2/5 with thrombotic events." (PMID 25497157, 2014). "Coagulation parameters were altered in 15/17 patients (88%) including significant decrease of factors IX, XI and XII, and less frequently of antithrombin III, protein C and protein S. Five patients presented blood count abnormalities, i.e. neutropenia (n = 2) or thrombocytopenia (n = 4)." (PMID 25497157, 2014).
varicella (6 papers, 2011 to 2025). "Anti-protein S antibodies are frequently found in the context of varicella, in contrast with the rarity of IPF." (PMID 37325350, 2023).
astrocytoma (5 papers, 2005 to 2022). "Our results indicate that alterations of SGCG, PROS1 and ITGB1 genes appeared prevalently in grade III astrocytomas and resulted in shorter survival of patients, implying more aggressive nature of tumors with this genetic signature." (PMID 24358143, 2013). "The prognosis of LGG patients with high PROS1 levels was poor in women, age > 40 years, 1p/19q non-codeletion, SD&PD, and astrocytoma subgroups." (PMID 35879775, 2022).
meningioma (5 papers, 2005 to 2026). A generally slow growing tumor attached to the dura mater. "Moreover, elevated levels of proteins involved in blood coagulation and hemostasis, such as antithrombin-3, alpha-2-antiplasmin, vitamin K-dependent protein S, fibrinogen alpha chain, plasminogen, alpha-2-macroglobulin, and coagulation factor ×2, were associated with different grades of meningiomas." (PMID 38001599, 2023).
paroxysmal nocturnal hemoglobinuria (5 papers, 2014 to 2023). Paroxysmal nocturnal hemoglobinuria (PNH) is an acquired clonal hematopoietic stem cell disorder characterized by corpuscular hemolytic anemia, bone marrow failure and frequent thrombotic events. "Other common causes comprise antiphospholipid syndrome, factor V Leiden thrombophilia, protein C and protein S deficiency, as well as paroxysmal nocturnal hemoglobinuria (PNH)." (PMID 34441027, 2021). "The thrombophilic screening (factor V Leiden mutation, prothrombin gene mutation, inherited deficiencies for protein C, protein S and antithrombin, anticardiolipin antibodies, lupus anticoagulant antibodies, paroxysmal nocturnal hemoglobinuria), including V617F JAK2 mutation, was negative." (PMID 23813023, 2014).
periodontitis (5 papers, 2019 to 2025). An acute or chronic inflammatory process that affects the tissues that surround and support the teeth. "Daily subcutaneous injection of 20 μg Pros1 in the ligature + p.g‐LPS group attenuated periodontitis‐mediated alveolar bone loss and osteoclastogenesis, showing a CEJ‐ABC distance and osteoclast number similar to those of the ligature only group." (PMID 30729671, 2019). "In rats treated with ligature and p.g‐LPS, administration of Pros1 attenuated periodontitis‐associated gingival inflammation and alveolar bone loss." (PMID 30729671, 2019). "In a mouse model of periodontitis induced by P. gingivalis, the loss of MyD88 in TLR signaling significantly reduced the expression of GAS6, AXL, and PROS1." (PMID 34734092, 2021). "The TAM receptors Tyro3, Axl and Mertk and their ligands Gas6 and Pros1 were detected by qRT‐PCR in gingival tissues of patients with chronic periodontitis as well as healthy controls with non‐inflamed gingiva." (PMID 30729671, 2019). "Collectively, the findings from this work supported Pros1 as a novel anti‐inflammatory therapy for periodontitis." (PMID 30729671, 2019). "The aim of the study was to clarify the specific role of Pros1/Tyro3 axis in regulating oral inflammatory disease such as periodontitis." (PMID 30729671, 2019). "While Gas6, Axl and Mertk were detected at similar levels in periodontitis and control gingiva, Pros1 was found to be up‐regulated and Tyro3 down‐regulated in periodontitis specimens compared with controls." (PMID 30729671, 2019). "In rats subjected to combinatorial treatment with ligature and p.g‐LPS, administration of Pros1 attenuated periodontitis‐mediated gingival inflammation, periodontal osteoclastogenesis and alveolar bone loss." (PMID 30729671, 2019). "To investigate the mechanisms involved in the protective effects of Pros1 against periodontitis in rats, we evaluated rat periodontal SOCS1/3 and STAT1/3 by Western blot analysis." (PMID 30729671, 2019). "In periodontitis patients, elevated Pros1 and decreased Tyro3 were detected in inflamed gingiva, while the expression of Gas6, Axl and Mertk was similar to that of healthy control." (PMID 30729671, 2019). "Collectively, the findings from this work supported Pros1 as a novel therapy to combat periodontitis." (PMID 30729671, 2019). "We detected higher Pros1 but lower Tyro3 levels in inflamed gingival specimens of periodontitis patients compared with healthy controls." (PMID 30729671, 2019). "Of note, the down‐regulation of Pros1 in the in vitro and in vivo models of periodontitis was opposite to the up‐regulation of Pros1 in inflamed human gingiva of periodontitis patients." (PMID 30729671, 2019). "In this study, we evaluated the effects of exogenous Pros1 in in vitro and in vivo models of periodontitis." (PMID 30729671, 2019). "Based on these data, we speculated that the Pros1/Tyro3 signalling may be the main TAM signalling involved in the development of periodontitis in humans." (PMID 30729671, 2019). "Furthermore, positive Pros1 staining was mainly detected in the gingival epithelium of both periodontitis patients and non‐inflamed controls." (PMID 30729671, 2019). "However, the mechanisms underlying immunoregulation of TAM receptor tyrosine kinases or their ligands during periodontitis, especially for Pros1, was yet to be elucidated." (PMID 30729671, 2019). "We next assessed Pros1, Tyro3 and RNAKL levels in periodontal tissues of periodontitis and sham rats." (PMID 30729671, 2019).
thalassemia (5 papers, 2009 to 2025). An inherited blood disorder characterized by a decreased synthesis of one of the polypeptide chains that form hemoglobin. "The hypercoagulable state in thalassemia is further exacerbated by reduced levels of natural anticoagulants, such as protein C and protein S, which contribute to thrombotic events." (PMID 39859141, 2025).
Behcet disease (4 papers, 2012 to 2025). A chronic, relapsing, multisystemic vasculitis characterized by mucocutaneous lesions, as well as articular, vascular, ocular and central nervous system manifestations. "Two SNPs within GAS6 and PROS1 genes contributing to the genetic susceptibility of Behçet’s disease were associated with the reduced transcription of corresponding genes." (PMID 40044635, 2025). "Likewise, single-nucleotide polymorphisms in GAS6- and PROS1-encoding genes are associated with Behçet’s disease, a condition characterised by multisystemic inflammations with recurrent ocular symptoms and ulcers in different organs." (PMID 40044635, 2025). "In several inflammatory and autoimmune diseases, including inflammatory bowel disease, MS, SS, Behcet’s disease, SLE, and psoriasis, plasma levels of GAS6 and PROS1 were lower than in healthy individuals." (PMID 40044635, 2025).
dilated cardiomyopathy (4 papers, 2011 to 2025). Cardiomyopathy which is characterized by dilation and contractile dysfunction of the left and right ventricles. "We report a case of a young male with combined protein C and protein S deficiency who presented with acute MI, worsened ventricular systolic function, and progressive declination of ejection fraction (EF) secondary to dilated cardiomyopathy (DCM)." (PMID 31259110, 2019).
dysfibrinogenemia (4 papers, 2014 to 2021). "The most prevalent inherited hypercoagulable states are factor V Leiden mutation, prothrombin gene mutation, MTHFR gene mutation, lupus anticoagulant, defects in protein S, protein C, and antithrombin, and dysfibrinogenemia." (PMID 27478635, 2016). "Prior to CVC implantation, patients were screened for APC resistance, protein S and protein C deficiency, and dysfibrinogenemia." (PMID 25317335, 2014).
liver cancer (4 papers, 2019 to 2025). An epithelial or non-epithelial malignant neoplasm that arises from the liver. "Notably, IHC staining revealed medium/high PROS1 and AXL expression in liver cancers." (PMID 38254761, 2024).
Portal vein thrombosis (4 papers, 2020 to 2025). Thrombosis of the portal vein and/or its tributaries, which include the splenic vein and the superior and inferior mesenteric veins. "In addition to portal vein thrombosis related to shunt formation and oral diuretics, AT-III deficiency, protein C, and protein S were observed." (PMID 39463911, 2024).
preeclampsia (4 papers, 2014 to 2025). Preeclampsia is a hypertensive disorder of pregnancy that is characterized by new-onset hypertension with proteinuria presenting after 20 weeks of gestation, and depending on mild or severe forms may initially present with severe headache, visual disturbances, and hyperreflexia. "The evidence regarding the association of protein S and protein C deficiency and preeclampsia is controversial." (PMID 25426334, 2014). "While some reported an association between protein S deficiency and an increased risk for this syndrome (especially for early onset preeclampsia) others could not demonstrate this effect." (PMID 25426334, 2014).
protein (4 papers, 2021 to 2025). "Indeed, some individuals with hereditary and acquired protein S deficiency may manifest normal total protein S levels, while harboring decreased free protein S antigen and declining protein S activity levels." (PMID 35815065, 2021). "Protein-C deficiency was significantly higher in the PCOS-RPL population when compared to the non-PCOS RPL population (21.7% and 10.9% respectively) and a non-significant trend toward a higher protein-S deficiency was additionally found." (PMID 38027110, 2023).
Stillbirth (4 papers, 2014 to 2025). Death of the fetus in utero after at least 22 weeks of gestation. "The aim of our study is to summarize available data on the effect of Factor V Leiden, Prothrombin G20210A and MTHFR mutation, Protein S, Protein C and Anithrombin deficiency on the prevalence of stillbirth." (PMID 40087172, 2025). "There is some evidence regarding the relation of protein S deficiency and increased risk of stillbirth and mid-trimester IUGR." (PMID 25426334, 2014). "In cases of non‐criteria APS, SNAPS, protein S deficiency, factor XII deficiency, or increased platelet aggregation, the first attempt of LDA resulted in miscarriage and stillbirth, and the second attempt of LDA was subsequently performed." (PMID 40145013, 2025).
transient cerebral ischemia (4 papers, 2013 to 2023). "Among these patients, protein S deficiency was diagnosed only in one person who, besides erythromelalgia, presented with one episode of transient ischemic attack." (PMID 25878908, 2015).
tuberculosis (4 papers, 2012 to 2025). A chronic, recurrent infection caused by the bacterium Mycobacterium tuberculosis. "Apart from high frequency of antiphospholipid antibody levels in a patient with tuberculosis, deficiency of protein S has been mentioned." (PMID 25888831, 2015). "Decreased concentrations of protein C were associated with tuberculosis in HIV-infected patients, whereas reduced protein S concentrations (deficits in concentrations of both total and free protein S) were associated with decreased survival time." (PMID 28363198, 2017).
uveal melanoma (4 papers, 2022 to 2025). A melanoma derived from melanocytes of the uveal tract. "The PROS1-MERTK interaction thus represents a promising target for the development of immunotherapies in uveal melanoma and potentially other cancers where this axis is active." (PMID 39535659, 2025). "In uveal melanoma, a malignancy of the eye, PROS1 is significantly upregulated in class 2 tumors characterized by the loss of BAP1—a tumor suppressor gene." (PMID 39535659, 2025).
ankylosing spondylitis (3 papers, 2021 to 2024). An autoimmune chronic inflammatory disorder characterized by inflammation in the vertebral joints of the spine and sacroiliac joints. "PROS1 emerges as a promising targeted drug candidate for the treatment of inflammatory disorders, including spinal cord injury and ankylosing spondylitis." (PMID 38613800, 2024). "PROS1 can be used as a targeted drug for the treatment of inflammatory diseases, such as spinal cord injury and ankylosing spondylitis." (PMID 36855207, 2023).
anticoagulant (3 papers, 2018 to 2024). "Primary antiphospholipid syndrome (lupus anticoagulant positive, decreased protein S level), with associated thrombotic events including iliofemoral DVT and right atrial thrombus." (PMID 39156320, 2024).
bacteremia (3 papers, 2017 to 2025). "A previous study showed that HIV-infected patients with bacterial sepsis had more profound deficiencies of free protein S, but that study did not assess associations with death." (PMID 28363198, 2017).
Budd-Chiari syndrome (3 papers, 2013 to 2025). "Analysis of 157 patients with Budd-Chiari syndrome in Japan revealed that 141 were idiopathic, 2 were deficient in protein C, 2 were deficient in protein S, and 1 was deficient in antithrombin." (PMID 24250338, 2013). "This case highlights the importance of considering inherited thrombophilic disorders, such as deficiencies in protein C, protein S, and antithrombin III, in young patients presenting with features suggestive of Budd‐Chiari syndrome." (PMID 41394931, 2025).
cerebral infarction (3 papers, 2011 to 2023). An ischemic condition of the brain, producing a persistent focal neurological deficit in the area of distribution of the cerebral arteries. "Neonates with cerebral infarcts were evaluated to rule out prothrombotic states like antiphospholipid antibodies (APLA), protein C, and protein S." (PMID 38161855, 2023).
deficiencies (3 papers, 2018 to 2024). "However, tests for protein C, protein S or antithrombin deficiencies, antiphospholipid antibodies and factor V Leiden mutation were negative in this case, indicating the possibility of other hypercoagulation mechanisms." (PMID 30053822, 2018). "Moreover, factor V Leiden and prothrombin G20210A polymorphisms were found to be more exclusive to White than to Asian people, whereas the prevalence of protein S, protein C, and antithrombin deficiencies were found to be higher in Asian populations than in White populations." (PMID 36675542, 2023).
diabetic nephropathy (3 papers, 2008 to 2023). "Other authors reported a higher plasma and urinary concentration of soluble TAM receptors (Tyro 3, Axl, Mer) and of their ligand (protein S) in patients with diabetic nephropathy." (PMID 35203408, 2022).
hematoma (3 papers, 2016 to 2026). A hematoma is a collection of blood from a vascular structure into an extravascular space. "Taken together, activation of the TAMreceptors-Gas6/Pros1-PtdSer pathway may provide a viable therapeutic approach toaccelerate hematoma resolution and promote neurological recovery after ICH." (PMID 41504200, 2025).
hypothyroidism (3 papers, 2022 to 2025). Abnormally low levels of thyroid hormone. "Hypothyroidism was associated, on the one hand, with decreased factor X activity and, on the other hand, with a decrease in the protein S level." (PMID 39323731, 2024). "Those with hypothyroidism had significantly reduced activity of coagulation factor X [by −30% (95% CI −47 to −13)] and protein S [by −27% (95% CI −41 to −13)] compared with euthyroid NS individuals." (PMID 39323731, 2024). "The effects of hypothyroidism on factor X and protein S activities were still prominent after adjustment for serum albumin as an indicator of NS severity." (PMID 39323731, 2024).
Intrauterine growth restriction (3 papers, 2023 to 2024). "Intrauterine growth restriction (IUGR), finally, showed a higher prevalence of heterozygosity for Factor II, homozygosity for the MTHFR C677T mutation, and protein S deficiency." (PMID 38534435, 2024).
myopia (3 papers, 2017 to 2025). "A diverse range of complement-related genes were differentially-expressed, with components and regulators of both the classical and alternate pathways up-regulated in late myopia (CS1, PROS1, C1QB and CFD) and late hyperopia (SERPING1, C1QA, CRP, C7 and CFD)." (PMID 28852117, 2017).
polycythemia (3 papers, 2016 to 2025). Abnormally high mass or concentration of red blood cells in the blood, either due to an increase in erythropoiesis or a decrease in plasma volume. "Our case had dehydration, polycythemia, decreased protein S activity, and history of an ascent to high altitude." (PMID 27872776, 2016).
pulmonary hypertension (3 papers, 2019 to 2021). Increased pressure within the pulmonary circulation due to lung or heart disorder. "At a 6-month follow up visit, PTE and pulmonary hypertension had disappeared but the patient still had a partial protein S deficiency." (PMID 32884835, 2020).
renal carcinoma (3 papers, 2012 to 2019). A carcinoma arising from the epithelium of the renal parenchyma or the renal pelvis. "As 786-0 renal carcinoma cells expressed ProS1 protein strongly, we used the conditioned medium from these cells and SCC-25 cells as responder cells to compare against the already observed effect of exogenous recombinant ProS1." (PMID 31766614, 2019).
retinal degeneration (3 papers, 2014 to 2020). Degeneration of the retina. "We have previously shown that Tyro3 mouse mutants, Gas6 mouse mutants, and retina-specific Pros1 mouse mutants all have a normal number of PRs at this time; but that Gas6/Pros1 double mutants display PR death and retinal degeneration that fully phenocopies the degeneration of the Mertk mutants." (PMID 25265470, 2014).
retinal vein occlusion (3 papers, 2004 to 2025). An occlusion of the retinal vein. "This case illustrates that protein S deficiency is a factor that should be considered in cases of retinal vein occlusion, particularly in young patients." (PMID 15448814, 2004). "Associated risk factors for events of retinal vascular occlusion are primary antiphospholipid antibody syndrome, high factor VIII, and low protein S." (PMID 35449024, 2022).
systemic sclerosis (3 papers, 2014 to 2022). A chronic disorder, possibly autoimmune, marked by excessive production of collagen which results in hardening and thickening of body tissues. "We only found published cases in which systemic arterial embolism occurred secondary to systemic sclerosis, malignant tumor, or protein C and protein S abnormalities." (PMID 27510310, 2016).
thalassemia major (3 papers, 2023 to 2025). "Red blood cells from thalassemia major (TM) and intermedia (TI) patients have been shown to adhere to cultured endothelial cells and express adhesion molecules and tissue factors in circulation, accompanied by decreased levels of protein C and protein S compared with healthy individuals." (PMID 41293405, 2025).
amyloid (2 papers, 2019 to 2022). "Here, we found that, consistent with the other complement proteins, PROS1 was increased in the hippocampus of 5XFAD mice at 10 months of age and, thus, is likely to be closely associated with amyloid pathology." (PMID 31727875, 2019).